SNAP25 (synaptosome associated protein 25)
Diseases named in the same sentence as SNAP25 in open-access papers (continued):
Sharing a sentence is not in itself a finding about the gene and the disease.
dementia (25 papers, 2009 to 2025). Loss of intellectual abilities interfering with an individual's social and occupational functions. "Blood levels of APOE and SNAP25 have been reported to be associated with dementia and suggested as biomarkers for dementia." (PMID 40877285, 2025). "SD-pQTLs for proteins APOE (rs157581) and SNAP25 (rs4420638) exhibited sex-dimorphic associations with dementia, indicating sex dimorphic pleiotropy in both proteins and health disorders." (PMID 40877285, 2025). "Higher levels of SNAP-25–syntaxin interaction (controlling for the level of SNAP-25 as well as for pathology) were associated with a lower likelihood of dementia." (PMID 33212853, 2020). "Recent results showed that a reduction of SNAP-25 is associated with dementia, and that the rs363050 SNAP-25 polymorphism correlates with cognitive decline and brain atrophy, as well as with the outcome of multistructured rehabilitation in AD patients." (PMID 30914946, 2019). "This speculation is supported by evidence showing that high levels of presynaptic proteins, including synaptophysin, SNAP-25, syntaxin, and synaptobrevin, are associated with better cognitive performance and a lower risk of dementia in older adults." (PMID 40507821, 2025). "CSF SNAP25 increases in AD, and SNAP25 1–40 can be used not only for diagnosis (AD vs controls, AUC: 0.93) but also for differential diagnosis (AD vs other dementia, AUC: 0.92)." (PMID 35306613, 2022). "SD-pQTLs of the proteins APOE (rs157581, chr19: 45,395,714) and SNAP25 (rs4420638, chr19: 45,422,946) exhibited a sex dimorphic effect on dementia, suggesting potential sex-dimorphic pleiotropy involving these proteins and dementia." (PMID 40877285, 2025). "Further investigation with the identified SD-pQTL of APOE and SNAP25 in this study could provide insight into the pathophysiology of dementia and help improve its prediction, diagnosis, and treatment." (PMID 40877285, 2025). "SNAP25 showed a significant association with prospective dementia only in females (HR = 1.24, p-value = 3.17E-04) but not in males (HR = 1.01, p-value = 0.838)." (PMID 40877285, 2025). "In the current study, we investigated the ability of SNAP‐25 to differentiate between heterogenous dementia etiologies and whether SNAP‐25 could be a staging marker in AD." (PMID 39912369, 2025). "Our initial findings suggest that SNAP‐25 may be a potential biomarker for differentiating AD from dementia due to other etiologies." (PMID 39912369, 2025). "Levels of PSD-95 and SNAP-25 were nominally higher in AD subjects with dementia (PSD-95: 312±161 pg/ml; SNAP-25: 180±73 pg/ml) compared to MCI in unadjusted analysis (p<0.05 for both comparisons), but this did not remain statistically significant after multiple testing correction." (PMID 35461266, 2022). "Synaptic proteins such as synaptosomal-associated protein 25 (SNAP-25) and synaptotagmin-1 (SYT1) were found to be significantly increased in the CSF of AD dementia and prodromal AD patients; however, SNAP-25 and SYT1 were specified to decline in cortical areas." (PMID 32708853, 2020). "We aimed to answer these questions by examining whether blood-based levels of VAMP2 and SNAP25 along with blood-based ATN(I) biomarkers are associated with SV2A PET in the brains of older adults without dementia." (PMID 40620474, 2025). "Synaptic loss is a common hallmark of dementia, involving both specific presynaptic as well as postsynaptic proteins, which are postsynaptic density protein (PSD-95), synaptosomal-associated protein 23 (SNAP-23), synaptosomal-associated protein 25 (SNAP-25), and synaptophysin (SYP)." (PMID 38068844, 2023). "SNAP-25 protein is also variable, with decreases reported in post-mortem DLB and PD with dementia patients and cultured mouse hippocampal neurons treated with PFFs38; and increases in α-syn overexpressing in mice." (PMID 38172128, 2024).
dementia (continued). "We hypothesize that higher CSF Ng and SNAP-25 levels (ie, reflective of more severe synaptic injury) will be associated with lower FC of the left and right precuneus seeds during resting state and the performance of the FNDT in individuals with MCI and mild AD dementia." (PMID 31271547, 2019). "It is often observed that GAP‐43, SNAP‐25, β‐synuclein, and neurogranin are not changed in non‐AD dementias." (PMID 40522075, 2025). "Orther than Ng, CSF synaptosomal-associated protein-25 (SNAP-25), in particular its soluble form SNAP-25aa40, has shown good accuracy in discriminating AD from HCs and non-AD dementias." (PMID 35453843, 2022). "We measured synaptophysin, PSD95, drebrin, SNAP-25, and septin 7 by ELISA in hippocampus and superior temporal gyrus from 103 adults aged <75 without dementia." (PMID 28731446, 2017). "In comparison with the control group and the dementia groups without LBs, the LBV group had significantly lower levels of syntaxin and SNAP-25 (23%) in the neocortex, and depletion of MAP2 (64%), SNAP-25 (34%), and α-synuclein (44%) proteins in the medial temporal lobes." (PMID 20024519, 2009).
cognitive decline (21 papers, 2014 to 2026). "Third, increase over time in levels of SNAP-25 and NfL were associated with faster cognitive decline in AD dementia patients." (PMID 39121126, 2024). "Higher baseline levels of SNAP25, β-syn, and 14-3-3 proteins were associated with faster cognitive decline (St.B[SE] –0.27[0.12] to –0.61[0.12])." (PMID 39121126, 2024). "Several studies have demonstrated that SNAP25 in cerebrospinal fluid was a potential synaptic biomarker, and was associated with cognitive decline in AD and PD patients." (PMID 38053192, 2023). "Consistently, in both Banner and BLSA, we found that lower-abundance of SNAP25 was associated with faster cognitive decline." (PMID 30962425, 2019). "Cerebrospinal fluid (CSF) candidate markers (CHI3L1, parvalbumin) and synaptic proteins (SNAP-25, neurogranin, β-synuclein) may help identifying patients at higher risk of cognitive decline." (PMID 41960777, 2026). "Furthermore, increase in NfL and SNAP-25 levels over time was associated with faster cognitive decline specifically in AD dementia patients, while on average in the total cohort these proteins did not increase over time." (PMID 39121126, 2024). "Interestingly, previous studies have shown evidence that SNAP-25 single nucleotide polymorphisms are associated with cognitive decline." (PMID 25418885, 2014). "Lower SNAP-25 in blood exosomes correlated with cognitive decline, providing an accessible biomarker for monitoring AD progression." (PMID 40864734, 2025). "This indicates that synaptic dysfunction precedes noticeable cognitive decline, positioning SNAP-25 as a marker of early pathological processes, including microglial activation and synaptic damage." (PMID 40864734, 2025). "Second, we showed that especially higher baseline levels of SNAP-25, and in lesser extent of NfL, Ng, β-syn, proteins of the 14-3-3 family, GDI-1 and PEBP-1 were associated with faster cognitive decline and disease progression along the AD continuum." (PMID 39121126, 2024). "Higher baseline levels of most proteins (SNAP-25, NfL, Ng, β-syn, γ-syn, AP2-complex subunit β [AP2], GDI-1, PEBP-1, all 14-3-3 proteins and CPLX2) were also associated with faster cognitive decline (interaction protein*time p < 0.05)." (PMID 39121126, 2024). "Analyses of human clinical testing and prototypic peptides show that higher levels of synaptic plasticity-related proteins, such SNAP25, SYT12, and VGF, and mitochondrial proteins, such as NDUFA, are associated with slower cognitive decline." (PMID 37338529, 2023). "Recent studies reported that CSF SNAP-25 increases in MCI and AD, which is associated with the rate of hippocampal atrophy and cognitive decline." (PMID 33926475, 2021). "For the synaptic biomarkers, in the temporal lobe, the trimeric SNARE protein interaction (SNAP-25, syntaxin, VAMP) is associated with the rate of cognitive decline and global cognitive function." (PMID 33212853, 2020). "This reinforced the hypothesis that SNAP-25 elevation correlates with synaptic damage and cognitive decline." (PMID 40864734, 2025). "The objective of the present study was to investigate if CSF SNAP‐25 could differentiate between AD disease stages and between cognitive decline of different etiologies." (PMID 39912369, 2025). "In summary, our findings demonstrated that inhibiting TNFAIP1-mediated degradation of SNAP25 might be a promising therapeutic approach for mitigating postoperative cognitive decline." (PMID 38102610, 2023). "Global cognitive decline is associated with reduced SNARE complex levels (Syntaxin1, SNAP25, VAMP)." (PMID 39086962, 2022). "We observed a significant decreased expression of MAP-2 (p = 0.016377), SNAP25 (p = 0.0128) and CAMK2 (p = 0.003930) suggesting that inhibition of Nrgn expression induced by overexpression of the lncRNA caused disruption of synaptodendritic integrity, which is implicated in cognitive decline." (PMID 38659061, 2024).
cognitive decline (continued). "However, it is still unknown whether CSF SNAP-25 levels increase at the early clinical stage of AD, and whether CSF SNAP-25 is correlated with other core features of AD such as amyloid-β (Aβ) pathology, structural brain changes, and cognitive decline." (PMID 30115118, 2018). "Neurodegeneration-based markers in CSF, including NF-L, VILIP-1, neurogranin, and SNAP-25, also showed high positive correlations with neuronal damage in AD and MCI and can be used for evaluation and prediction of future cognitive decline in AD." (PMID 32806668, 2020). "In the retrospective study, significantly elevated SNAP‐25 levels were seen in MCI due to prodromal AD compared to both HC and AD, although less cognitive decline was observed in MCI due to prodromal AD as compared to AD, as indicated by the MMSE score, as expected." (PMID 39912369, 2025). "In the present study, there was a negative correlation between SNAP-25 (Ac-2-16) and the MMSE, indicating patients suffering from more severe cognitive decline had higher levels of SNAP-25 (Ac-2-16), which implies that the novel biomarker might be useful to follow progression of cognitive decline." (PMID 25418885, 2014).
neuroblastoma (19 papers, 2008 to 2026). Neuroblastoma (NB) is the most common solid, extracranial childhood tumor. "Botulinum toxin C that cleaves SNAP25 and Syntaxin1 caused the apoptosis of differentiated neuroblastoma cells." (PMID 39195765, 2024). "A cell-based potency assay was developed for onabotulinumtoxinA (Botox, Allergan Inc., Dublin, Ireland) that utilizes differentiated human neuroblastoma SiMa cells and a sandwich enzyme-linked immunosorbent assay readout, which measures BoNT-A-dependent intracellular increase of cleaved SNAP-25." (PMID 37235349, 2023). "Our mechanistic insights revealed that loss of ubiquitous SNAP23 due to differentiation coupled to SNAP25 cleavage due to botulinum activity may underlie the apoptotic death of human neuroblastoma cells." (PMID 27121208, 2016). "This indicates that the depletion of SNAP25 caused by BoNT/C in differentiated neuroblastoma cells may result in cell death." (PMID 27121208, 2016). "SNAP25 was reported to be implicated in neuritogenesis in human neuroblastoma." (PMID 21114830, 2010). "To validate the behavior of SNAP25, we therefore relied on a super-resolution imaging assay, in which we tested its localization, in comparison to endogenous SNAP25, in a neuroblastoma cell line (PC12)." (PMID 38079451, 2023). "The BoCell® cell line is an engineered murine neuroblastoma cell line that stably expresses a reporter composed of SNAP-25 fused to cyan and yellow fluorescent proteins (CFP, YFP) on the N- and C-terminals of SNAP-25, respectively." (PMID 37235349, 2023). "One of these clones (SNAP1) was further reformatted into a scFv-Fc antibody and was shown to bind the peptide with extremely high affinity and to specifically recognize the product of BoNT/E cleaved SNAP-25 in human neuroblastoma cells." (PMID 35323195, 2022). "Our results show that BiTox/AA can cleave SNAP-25 similar to BoNT/A and at a similar rate in human SiMa neuroblastoma cultures." (PMID 33205382, 2021). "Next, we compared the cleavage of neuronal SNAP-25 by BiTox/AA against native BoNT/A in human neuronal cultures derived from SiMa neuroblastoma cells." (PMID 33205382, 2021). "An increase in SNAP-25 expression was reported in neuroblastoma SH-SY5Y cells during neuritogenesis, and is overexpressed in tumor cells of prolactinomas." (PMID 32545553, 2020). "The inhibition of PP1 by TMC increased the phosphorylation of SNAP-25 at Thr138 in B50 neuroblastoma cells, in KCl-depolarized cortical synaptosomes, and in cortical thin brain slices." (PMID 28486561, 2017). "To further study the interaction between SNAP-25 and the subunits of myosin phosphatase, we carried out reciprocal immunoprecipitations from B50 neuroblastoma cell lysates using specific anti-SNAP-25, anti-PP1cδ and anti-MYPT11-296 antibodies." (PMID 28486561, 2017). "In conclusion, we have shown that ROK phosphorylates and MP dephosphorylates SNAP-25 at Thr138 in synaptosomes, cortical thin slices and B50 neuroblastoma cells to regulate the assembly of the SNARE complex and neuronal exocytosis." (PMID 28486561, 2017). "This suggests that MP dephosphorylates SNAP-25 on Thr138 in B50 neuroblastoma cells and this dephosphorylation can be diminished by silencing of MYPT1, the targeting subunit of the dephosphorylation process." (PMID 28486561, 2017). "First, we ascertained the presence of the SNARE proteins syntaxin, SNAP25, and synaptobrevin in mouse neuroblastoma N2A cells by confocal microscopy." (PMID 24372287, 2014). "In Neuro-2a neuroblastoma cells, the 4LCA antibody prevented the cleavage of the BoNT/A proteolytic target, SNAP-25." (PMID 18714390, 2008). "In the first assay, we tested the ability of the 4LCA to inhibit cleavage of SNAP-25, the proteolytic substrate of the BoNT/A LC, in Neuro-2a murine neuroblastoma cells." (PMID 18714390, 2008). "ChoBot also mediated SNAP25 cleavage in human neuroblastoma cells in culture." (PMID 42043038, 2026).
neuroblastoma (continued). "Silencing MYPT1 in B50 neuroblastoma cells increased phosphorylation of SNAP-25 at Thr138." (PMID 28486561, 2017). "Immunoblotting revealed a massive cleavage of Syntaxin 1 and SNAP25 in neuroblastoma cells." (PMID 27121208, 2016). "We observed that Bitox, which carries the native BoNT/A targeting domain, could cleave SNAP25 in SH-SY5Y neuroblastoma cells, which is in accord with the ability of native BoNT/A to target these cells." (PMID 23638840, 2013). "The B8-TrCP TFB fusion protein or ALcB8 alone were expressed within BoNT/A intoxicated neuroblastoma Neuro 2A (N2A) cells together with the ALc substrate, SNAP25, expressed as an indicator protein flanked by yellow fluorescent protein (YFP) and cyan fluorescent protein (CFP)." (PMID 21629663, 2011). "Indeed, certain serotypes of botulinum neurotoxins specifically cleave SYN or SNAP25, causing cell degeneration in neurons, but not in different cell lines, such as neuroblastoma cell lines or primary glia cells." (PMID 40553089, 2025). "Finally we tested whether the levels of intact SNAP25 recover more rapidly following BoNT/A intoxication of neuroblastoma cells when expressing the ALc-targeting TFB, D5-B8." (PMID 21629663, 2011). "Co-localization of SNAP-25 and MYPT in the cytoplasm and neuronal projections of B50 neuroblastoma cells was detected using confocal microscopy." (PMID 28486561, 2017). "We have utilized model neuroblastoma cells (N2A) that abundantly express all three neuronal SNARE proteins: syntaxin 1, SNAP25, and synaptobrevin 2 (Syb2)." (PMID 24372287, 2014). "Thus, when undifferentiated, neuroblastoma cells do not likely require SNAP25 or syntaxin 1 for cell survival and growth." (PMID 27121208, 2016).
attention deficit-hyperactivity disorder (16 papers, 2008 to 2024). A disorder characterized by a marked pattern of inattention and/or hyperactivity-impulsivity that is inconsistent with developmental level and clearly interferes with functioning in at least two settings (e.g. at home and at school). "For example, mutations in the SNAP-25 gene have been associated with Attention-deficit Hyperactivity Disorder (ADHD) and bipolar disorder." (PMID 29051423, 2016). "Synaptosomal-associated protein of 25 kDa (SNAP-25) regulates exocytosis of neurotransmitters and is thought to be involved in the neuropsychiatric disorders such as schizophrenia, attention-deficit/hyperactivity disorder (AD/HD), and epilepsy." (PMID 23840971, 2013). "In man, SNAP-25 function has been linked to behavioral and neuropsychiatric disorders, including attention deficit hyperactivity disorder, ADHD." (PMID 19043548, 2008). "Finally, genetic studies have demonstrated an association of polymorphisms in the human SNAP-25 gene with attention deficit hyperactivity disorder or cognitive performance." (PMID 19424436, 2009).
coloboma (14 papers, 2005 to 2025). An abnormality in which a part of a structure in one or both eyes is missing. "The coloboma mutant (CM) mouse was developed through neutron irradiation, which induced a mutation on chromosome 2, disrupting several genes, including synaptosomal-associated protein 25 kDa (SNAP-25)." (PMID 40988072, 2025). "We show that ADHD-associated variants of SNAP25 influence expression within the IFG, with decreased SNAP-25 expression (as expected from the Coloboma mouse) associated with the ADHD risk variants." (PMID 23593184, 2013). "The SNAP-25 deficient mouse mutant coloboma (Cm/+) is of interest to ADHD because SNAP-25 polymorphisms have been associated with the disorder." (PMID 16022733, 2005). "The SNAP-25 deficient mouse mutant coloboma displays spontaneous hyperactivity but lacks impulsiveness and has not been shown to have problems with sustained attention." (PMID 16022733, 2005). "As SNAP-25 has multiple functions and affects many transmitters and ion channels, the superficial phenotypic resemblance of Coloboma mice to ADHD can hardly be attributed only to the DA system." (PMID 39619336, 2024). "In one study, reduced SNAP‐25 gene expression and spontaneous hyperkinetic behavior in the mouse coloboma (Cm) mutant strain demonstrated the importance of the SNAP‐25 gene in ADHD." (PMID 36068994, 2022). "Similar to the situation in Gnpat KO mice, the 50% reduction of SNAP-25 in the coloboma mouse presumably affects all synapses, independently of the neurotransmitter system." (PMID 30759250, 2019). "The coloboma mouse model, characterized by halved SNAP-25 levels, displays indeed a hyperactive phenotype, associated with abnormal thalamic spike-wave discharges." (PMID 27047369, 2016). "The Coloboma mouse carries a ∼2 cM deletion encompassing the SNAP25 gene and has a hyperactive phenotype similar to that of ADHD." (PMID 23593184, 2013). "The coloboma mouse, which is the animal model of ADHD has SNAP-25 deficiency and changes in SNAP-25 expression were shown to play a role in altered neuronal function." (PMID 24391914, 2013). "The Coloboma mouse, another frequently used mouse model of ADHD, has mutations in the genes encoding SNAP-25 and phospholipase C-β1, and exhibit profound hyperactivity, which is reduced by amphetamine, but not by methylphenidate." (PMID 22558465, 2012). "Taking all these considerations into account, we propose that coloboma mutant mice or Snap25-mutant mice could be used as promising models for ADHD." (PMID 38605002, 2024). "Thus, the coloboma mouse model, characterized by halved SNAP-25 levels, displays a hyperactive phenotype, associated with abnormal thalamic spike-wave discharges." (PMID 34512248, 2021). "In addition, this mouse model has a mutation in the synaptosome-associated protein 25 (SNAP25) gene, and the authors suggest that the behavioural performance of coloboma mice could be related to SNAP25 dysfunction." (PMID 35886894, 2022).